EGFR (epidermal growth factor receptor)
Diseases named in the same sentence as EGFR in open-access papers (continued):
Sharing a sentence is not in itself a finding about the gene and the disease.
glioblastoma (continued). "First, recent studies indicate that EGFR in glioblastoma occurs in several forms, including EGFRvIII, EGFR with kinase domain duplication (EGFR-KDD), EGFR fused with SEPT14 (EGFR-SEPT14), and EGFR with point mutations in both intracellular and extracellular domains." (PMID 35456993, 2022). "MiR-146b decreased expression of EGFR, glioblastoma cell migration and viability." (PMID 36536420, 2022). "Two fusions had previously been associated with glioblastoma: FGFR3::TACC3 and EGFR::SEPTIN14." (PMID 36002559, 2022). "They cloned a construct including a CAR specific for EGFRvIII, a glioblastoma-specific tumor antigen, that upon activation leads to the local secretion of a bispecific T cell engager (BiTE) against EGFR, an antigen frequently overexpressed in glioblastoma, but also expressed in normal tissues." (PMID 35158839, 2022). "In addition, we also treated three patients with anti-EGFR ILs-dox before resection of their relapsed glioblastoma." (PMID 34998092, 2022). "Cancer cells, including preclinical glioblastoma tumor models, express EGFR." (PMID 35884906, 2022). "It was reported that glutamate may alter glioblastoma malignant progression by stimulating the epidermal growth factor receptor signaling pathway." (PMID 36405708, 2022). "For glioblastoma-relevant targets, this includes EGFRvIII, EGFRvIII/EGFR, HER2, and CD133." (PMID 33753869, 2022). "For, instance, the EGFR gene expression has been altered in glioblastoma." (PMID 35804989, 2022). "Using the TTD database, we discovered that EGFR, ABAT, and PDGFRA are strongly associated with AQP4 expression in the glioblastoma (GBM) classification, and these factors could be the potential AQP4-related immunotherapy targets." (PMID 36523816, 2022). "Since overexpression of Epidermal Growth Factor Receptor (EGFR) is common in many glioblastoma patients, it could also be considered a potential target." (PMID 36230481, 2022). "The relatively lower frequency observed in our cohort may be a consequence of the fact that samples were sourced globally from different ethnic populations and also included secondary glioblastomas in which EGFR amplification events are a rare event." (PMID 35324914, 2022). "Overall, despite the presence of EGFR amplification in all four cases, a diagnostic molecular marker in IDH-wildtype glioblastoma and a predictor of its aggressive behavior, IDH-mutant status was the determinate factor for an epigenetics-based classification of these high-grade astrocytomas." (PMID 35669011, 2022). "We enrolled nine eligible patients with relapsed glioblastoma and EGFR amplification." (PMID 34998092, 2022). "An IDH wildtype adult-type diffuse glioma is diagnosed as a glioblastoma (CNS WHO grade 4), and they frequently have telomerase reverse transcriptase (TERT) promoter mutations, chr7 gain and chr10 loss and/or EGFR (epidermal growth factor receptor) amplification." (PMID 36428772, 2022). "In glioblastoma, classical subtype is characterized with EGFR amplification." (PMID 35436989, 2022). "As in glioblastoma, EGFR-driven metabolic phenotypes may be responsible for the resistance of pHGG to metabolic drugs such as the imipridones (e.g. ONC201)." (PMID 35978801, 2022). "However, attempts to treat glioblastoma with targeted EGFR tyrosine kinase inhibitors (TKIs), such as erlotinib, gefitinib, lapatinib, and afatinib, have remained largely unsuccessful." (PMID 35456993, 2022). "There remains no appropriate parameter for predicting the response of glioblastoma to bevacizumab as precisely as epidermal growth factor receptor (EGFR) mutation predicts the response to tyrosine kinase inhibitor (TKI) treatment." (PMID 36091179, 2022). "Genetic EGFR alterations have been found in about 60% of glioblastoma patients, leading to uncontrolled activation of signalling pathways (MAPK, PI3K/AKT, JAK/STAT, NF-κB, AKT, and others), which in turn promote cell and tumour growth, apoptosis resistance, and angiogenesis." (PMID 35214064, 2022).
glioblastoma (continued). "SPOCD1 encodes a TFIIS-family transcription factor and has been reported to promote the progression and metastasis of several types of cancer, including bladder and ovarian cancers, and osteosarcoma and glioblastoma, by activating signaling pathways such as the EGFR and VEGFR pathways." (PMID 35976950, 2022). "EGFR amplification has significant specificity for glioblastomas." (PMID 35494014, 2022). "The statistical analysis illustrated that the EZH2/p65 axis was dramatically relative to age, glioma grades and EGFR expression, suggesting that high levels of both p65 and EZH2 expression are correlated to a higher risk of glioblastoma development and progression." (PMID 36263173, 2022). "Previous studies on epidermal growth factor receptor in glioblastoma multiforme patients." (PMID 35911278, 2022). "Our studies showed that erlotinib, an EGFR inhibitor, when combined with luteolin, could induce apoptosis and decrease cell proliferation in glioblastoma cell lines expressing EGFR vIII." (PMID 36199696, 2022). "The epidermal growth factor receptor (EGFR) is involved in various developmental processes, and alterations of its extracellular segment are associated with several types of cancers, in particular glioblastoma multiforme (GBM)." (PMID 35232398, 2022). "•There is widespread chromatin disorganization in EGFR-amplified glioblastoma." (PMID 35521558, 2022). "Although the somatic mutational profiles of gliomas between East Asians and non-East Asians were broadly consistent, a lower incidence of EGFR amplification in glioblastoma and a higher incidence of 1p19q-IDH-TERT triple-negative low-grade glioma were observed in East Asian cohorts." (PMID 36350002, 2022). "This agent was chosen to test its ability to inhibit the growth of EGFRvIII+ glioblastoma because of the hypothesized synergistic effect of its components in disrupting EGFR signaling." (PMID 35456993, 2022). "Epidermal growth factor receptor (EGFR) is known to promote glioblastoma proliferation." (PMID 35205289, 2022). "In addition, upregulation of epidermal growth factor receptor (EGFR) was observed in more than 30% cases with glioblastoma and suppression of EGFR greatly blocks cancer cells development." (PMID 36118855, 2022). "All these alterations contribute to the tumorigenesis in EGFR-amplified glioblastoma." (PMID 35521558, 2022). "Moreover, MUC4 is co-expressed with MMP9 and EGFR in the proliferative microvasculature of glioblastoma, suggesting a potential role for MUC4 in microvascular proliferation and angiogenesis." (PMID 36400876, 2022). "Moreover, ABT-414 showed no impact on the health-related quality of life and neurological deterioration-free survival in EGFR-amplified recurrent glioblastoma, except for irreversible ocular toxicity, an expected side effect from MMAF." (PMID 35295841, 2022). "However, targeting EGFR in glioblastoma is particularly challenged by the amplification of extrachromosomal DNA, which contributes to significant variability in the expression of EGFRvIII." (PMID 34830952, 2021). "Moreover, the activation of FPRs leads to the transactivation of epidermal growth factor receptor (EGFR) in the glioblastoma cells." (PMID 34650406, 2021). "Furthermore, in a glioblastoma multiforme mouse model, a minor population that harbours mutant EGFR promoted the growth of EGFR wild type cells within the same tumour." (PMID 33803675, 2021). "For example, EGFR alterations and TERT promoter mutations are associated with poor prognosis, whereas IDH mutations and MGMT promoter methylation are associated with favorable prognosis in glioblastoma patients." (PMID 34732244, 2021). "At the molecular level, we discovered a so-far-unknown protein complex consisting of Lamellipodin and RICTOR and that Lamellipodin mediates glioblastoma radiation survival via EGFR signaling." (PMID 34771501, 2021). "EGFR is altered in approximately 50% of glioblastoma patients." (PMID 34648115, 2021).
glioblastoma (continued). "Thus, our data suggest an interdependency of EGFR and Lpd in the glioblastoma radioresponse, whereby EGFR exerts a positive effect on Lpd phosphorylation and Lpd negatively regulates EGFR levels and phosphorylation." (PMID 34771501, 2021). "Our results demonstrate that EGFR (HER1) signaling affects AR activation in glioblastoma." (PMID 34681618, 2021). "EGFR signaling is involved in AR activation in glioblastoma." (PMID 34681618, 2021). "Based on this and the significant role of EGFR in glioblastoma, we explored whether AR activation in glioblastoma is achieved through EGFR signaling." (PMID 34681618, 2021). "However, another study reported that mutations in extracellular domains I (R108K) and II (A209V) of EGFR in glioblastoma lead to ligand-independent phosphorylation." (PMID 33705793, 2021). "Considering its major role in glioblastoma, we explored whether EGFR is involved in AR signaling in this tumor." (PMID 34681618, 2021). "Furthermore, DYRK1A suppression can promote the degradation of EGFR and reduce the self-renewal capacity of glioblastoma cells." (PMID 34445786, 2021). "Overexpression of EGFR is observed in 40% of the primary glioblastomas." (PMID 34582442, 2021). "More recently, EGFRvIII‐targeted CAR‐T cells were constructed to secrete engagers against wild‐type EGFR for local recruitment of bystander T cells against EGFRvIII‐negative tumour cell subpopulations in glioblastoma, so as to overcome the limitation of antigen escape." (PMID 34585512, 2021). "Most glioblastomas have an amplification of the wild-type epidermal growth factor receptor gene (EGFR), which results in an increased RNA expression; this amplification can be detected (indirectly) by quantitative reverse transcriptase-PCR (qRT) of CSF-derived EV RNA." (PMID 34771592, 2021). "Moreover, they registered EGFR amplification, a primary glioblastoma attitude, and we confirmed this finding." (PMID 34698304, 2021). "mRNA and protein overexpression of LANCL2 and EGFR was also frequently found in glioblastoma." (PMID 34461927, 2021). "Moreover, we will delve deeper into genotyping our model for numerous interests, including CDKN2A deletion, EGFR amplification, IDH1/2, FGFR-TACC3, and H3K27M mutation because of their prevalence in human glioblastoma." (PMID 34884748, 2021). "EGFR-targeted nanobodies conjugated with inhibitors of invasion and migration in glioblastoma could lead new treatment strategies." (PMID 34769339, 2021). "Further, it was proposed that SEL1L could be an important biomarker in pTERT mutant/EGFR amplified/IDH wild-type subgroup of glioblastoma." (PMID 33547950, 2021). "In other human solid tumors such as colorectal cancer, head and neck squamous cell carcinoma, nasopharyngeal cancer, glioblastoma, and pancreatic cancer, the overexpression of EGFR was observed and EGFR-targeting agents were approved by the FDA for the treatment of these tumors." (PMID 34681198, 2021). "Additionally, in glioblastoma cells, CD44s attenuated EGFR degradation and sustained AKT signalling by the inhibition of Rab7A, which mediated EGFR trafficking for degradation, thus sustaining EGFR levels." (PMID 34944493, 2021). "These tracers target membrane proteins whose expression is altered in glioblastoma (including the EGFR, DLL4, EPHA2, CD47, AC133 antigen, and MT1-MMP): several components of the tumor microenvironment including vessels, macrophages, and extracellular matrix proteins." (PMID 35008238, 2021). "EGFR is a commonly altered oncogene in other solid epithelial cancers, such as colorectal cancer, head and neck cancer, pancreatic cancer, breast cancer, and glioblastoma." (PMID 34069119, 2021). "By inhibiting HB-EGF activity with neutralizing antibodies, EGFRvIII-induced cell proliferation may be reduced, suggesting that EGFRvIII-HB-EGF-wild-type EGFR autocrine loop has a major role in signal transduction in glioblastoma cells." (PMID 33435537, 2021).
glioblastoma (continued). "This TRAF2–DYRK1A–SPRY2 axis regulates the stability of EGFR, which could be significant in the EGFR-dependent glioblastoma or other cancers." (PMID 34117217, 2021). "In glioblastomas, several members of the SPRY family are included in a transcriptome module associated with the EGFR amplification status in GBMs, suggesting that they could act as oncogenes." (PMID 34445786, 2021). "EGFR and MEOX2 overexpression have been implicated before as drivers of glioblastoma growth." (PMID 34584066, 2021). "EGFR VIII, an oncogenic variant, could accelerate glioblastoma growth, but it also makes cells more sensitive to the EGFR tyrosine kinase inhibitor (TKI)." (PMID 34568472, 2021). "Given that excessive EGFR level enhances the proliferative capacity of glioblastoma, we additionally tested whether finasteride could modulate EGFR expression." (PMID 34575486, 2021). "Moreover, WTAP, an important component of the m6A methyltransferase complex, can regulate migratory and invasive capabilities of glioblastoma cells by increasing expression of epidermal growth factor receptor (EGFR)." (PMID 33718165, 2021). "In addition, TF expression in glioblastoma cells mediated by EGFR overexpression or EGF stimulation was JNK1 dependent." (PMID 34205482, 2021). "The EGFR gene is amplified in approximately 40% of glioblastomas." (PMID 33435537, 2021). "Moreover, the presence of TERT promoter mutations, EGFR alterations, or a combination of chromosome 7 gain and 10 loss upgrade IDH-wildtype astrocytoma to glioblastoma." (PMID 34638714, 2021). "HBEGF is a ligand for the EGFR, one of the most commonly amplified receptor tyrosine kinases in glioblastoma, which may be a clinically relevant target." (PMID 33828969, 2021). "Additionally, TERT promoter mutations, EGFR alterations, and 7+/10− upgrade IDH-wildtype astrocytomas to glioblastomas." (PMID 34638714, 2021). "Thus, our results suggest that Lpd, RICTOR and EGFR lie within the same signaling axis for the regulation of glioblastoma cell radiosensitivity." (PMID 34771501, 2021). "Furthermore, it was reported that inhibition of DYRK1A destabilizes EGFR and reduces EGFR-dependent glioblastoma growth." (PMID 34445786, 2021). "Interestingly, A172 cells showed the highest EGFR and Lpd phosphorylation among the investigated glioblastoma cell lines." (PMID 34771501, 2021). "Importantly, intravenous administration of nanocells carrying miR-34a and targeted to epidermal growth factor receptor (EGFR) strongly enhanced TMZ sensitivity in an orthotopic patient-derived xenograft mouse model of glioblastoma." (PMID 33765907, 2021). "In addition to deregulated phosphorylation of the well-known glioblastoma driver EGFR, we mainly identified deregulated members of the PI3K-AKT-mTOR pathway, MAPK pathway as well as small GTPase signaling upon X-ray irradiation." (PMID 34771501, 2021). "Concerning the positive effect of IL-15 on NK cell persistence, tumor infiltration, and functionality, a herpes simplex-1-based oncolytic virus expressing IL-15/IL-15Rα has resulted in highly significant anti-glioblastoma effects in combination with EGFR CAR NK cells." (PMID 34943898, 2021). "EGFRvIII is found in about 60% of EGFR-amplified glioblastomas." (PMID 33801941, 2021). "Furthermore, in glioblastoma, EGFR was shown to induce uPA expression by proto-oncogene tyrosine-protein kinase Src (c-Src) and ERK signaling." (PMID 33886813, 2021). "Therefore, cinobufagin blocks EGFR/STAT3 signaling in glioblastoma and shrinks brain tumors, elongating nude animal survival." (PMID 34925034, 2021).
glioblastoma (continued). "However, the amplification of EGFR is retained in recurrent glioma, although improved long-term survival by EGFRvIII therapy has been reported in glioblastoma patients." (PMID 33435537, 2021). "The bioinformatic analysis indicated that patients with higher lncRNA HULC expression in their GBM tissues had a worse prognosis, and lncRNA HULC overexpression promoted the proliferation, migration, and invasion of human glioblastoma U87 cells by enhancing the HIF‐related PI3K/AKT/EGFR signaling." (PMID 34213079, 2021). "Although alteration of purine metabolism has not been exclusively associated with specific oncogenic events in cancer, many oncogenic alterations that drive glioblastoma formation, including of PTEN, EGFR, and PI3CA, can cause similar alternations in nucleotide synthesis and metabolism." (PMID 34205450, 2021). "Since AKT is a known secondary messenger that plays a role downstream of EGFR signaling in glioblastoma, we explored whether AKT is involved in EGFR-induced AR regulation." (PMID 34681618, 2021). "A possible compensatory mechanism may also take place in glioblastoma where there is an increased expression of both uPA and uPAR in response to EGFR inhibition, favoring resistance to EGFR-targeted therapy." (PMID 33886813, 2021). "Moreover, we have provided evidence to confirm the role of miRNA-7 in glioblastoma erlotinib resistance, possibly in part via regulation of EGFR expression." (PMID 32592373, 2020). "The development of a specific molecular method allowing the simultaneous detection of EGFR alterations may be of interest in glioblastoma." (PMID 32303258, 2020). "This heterogeneity can alter cellular phenotypes, for instance, glioblastoma cells in hypoxic regions have been shown to over-express epidermal growth factor receptor (EGFR) while those over-expressing platelet-derived growth factor receptor (PDGFRA) were enriched in vascular regions." (PMID 32426371, 2020). "Furthermore, in glioblastoma cells, epidermal growth factor receptor (EGFR) can promote SREBP-1 cleavage and nuclear translocation through EGFR-PI3K-Akt signaling, without depending on mTORC1 activity." (PMID 33364199, 2020). "One Drosophila model of glioblastoma is based on co-activation of EGFR and PI3K in glial cells." (PMID 32073402, 2020). "In primary glioblastoma, EGFR is considered overexpressed in 63% of cases." (PMID 32349263, 2020). "For example, miR-7 is down-regulated in human glioblastoma and directly targets EGFR expression." (PMID 33369441, 2020). "The therapeutic efficacy of PIT has been demonstrated in multiple pre-clinical animal models of human cancers including breast (HER2), pancreatic (carcinoembryonic antigen), bladder (EGFR), prostate (prostate-specific membrane antigen), glioblastoma (mesothelin and EGFR), and melanoma (EGFR)." (PMID 32899183, 2020). "It targets the epidermal growth factor receptor and functions as a tumor suppressor in glioblastomas; it also targets Dickkopf‐1 in the Wnt/β‐catenin pathway, thereby functioning as an oncogene in tongue squamous cell, testicular germ cell, esophageal squamous cell, and prostate cancer." (PMID 32118353, 2020). "Also supporting our current findings, it has been shown that BCL6 depletion in glioblastoma cells sensitized these cells to the EGFR-TKI erlotinib." (PMID 32234966, 2020). "Our results suggest that modulating miR-200c may serve as a novel therapeutic approach for glioblastoma depending on EGFR status." (PMID 33396457, 2020). "Despite being found in over half of all glioblastomas, EGFR alterations remain an elusive target." (PMID 33187135, 2020).